TET2 (tet methylcytosine dioxygenase 2)
Diseases named in the same sentence as TET2 in open-access papers (continued):
Sharing a sentence is not in itself a finding about the gene and the disease.
cancer (continued). "This study aimed to demonstrate the overview of the TET2 gene in multiple female cancers and provide a foundation for the study of such cancers." (PMID 35223782, 2022). "The level of TET2 and 5hmC is widely decreased in cancer cells and can be used as a marker of the degree of cancer malignancy." (PMID 35480097, 2022). "To understand the molecular mechanism of TET2 in cancer immunotherapy, we employed RNA sequencing (RNA-seq) to identify the impact of vitamin C treatment and TET2 depletion on the transcriptome of RCC cells." (PMID 35173532, 2022). "Patients with different cancers were divided into the high- and low-expression groups based on the median TET2 expression level." (PMID 35223782, 2022). "The TET2 CD decreased the tumorigenic potential of cancer cells through both activation and repression of a repertoire of genes that, interestingly, differed in part from the one observed upon treatment with the hypomethylating agent decitabine." (PMID 35351824, 2022). "Aberrant methylation patterns are often associated with frequent mutations in genes that regulate DNA methylation (such as DNMT3a and TET2) in human cancers, leading to abnormal gene expression in human cancers." (PMID 35140720, 2022). "The DNMT3A R882H mutant combined with TET2 inactivation plays a role in DNA methylation dysregulation and induces malignant tumors in the mouse lymphatic system." (PMID 36428791, 2022). "Among the 15 canonical genes associated with CH, our cancer patients had mutations in CHEK2, DNMT3A, ASXL1, PPM1D, and TET2 only." (PMID 35428225, 2022). "TET1 and TET2 activities are also downregulated in several types of cancer by XPO1-mediated nuclear exportation, which can be restored by the XPO1 inhibitor leptomycin B (LMB)." (PMID 36203205, 2022). "Detailed analysis demonstrated that Tet1 antagonizes Tet2 in the regulation of HSC self-renewal and malignant myeloid development but compensates for Tet2 in preventing B and T lymphocytic malignancies." (PMID 36203205, 2022). "A pooled analysis was performed to examine the association between TET2 expression and OS, DFI, DSS, and PFI in major female cancers in TCGA." (PMID 35223782, 2022). "The degree of methylation at two promoter CpG sites was significantly less in TET2-high iCCA than in TET2-low iCCA or non-cancer tissue." (PMID 34905094, 2022). "The “pathological stage plot” module of GEPIA2 was used to observe the correlation between TET2 expression and pathological stages of cancer." (PMID 35223782, 2022). "Continued progress in preclinical experiments based on cell lines and animal models will help improve the survival rate of patients with TET2 mutant malignant tumors." (PMID 36428791, 2022). "Similar to the results of most studies of other malignant tumors, the results of our EC studies showed decreased TET2 and 5hmC expression in cancer tissues." (PMID 35480097, 2022). "The small difference in methylation values between the two groups is expected as the methylation change will only be occurring in the subpopulation of cells in the cancer tissue sample which express TET2." (PMID 34905094, 2022). "We demonstrated an association between the TET2/DNMT3A mutations and growth inhibition of cancer cells by T-dCyd treatment across 17 human solid tumor cell lines." (PMID 34039392, 2021). "Our results provide another link between downregulated Notch1 signaling and cancer cells with diminished TET2 function and suggest a therapeutic potential of Notch receptor agonists in this setting." (PMID 34622806, 2021). "Tet2 was originally recognized for its role in cell differentiation, embryonic development and cancer." (PMID 35011643, 2021). "The DNMT3A, TET2 and ASXL1 genes had the most mutation sites in different cancer types from the Chinese populations." (PMID 34658138, 2021). "Compared with TET2 which is frequently mutated in hematopoietic malignancies, TET1 mutation is a rare occurrence in cancer." (PMID 34957093, 2021).
cancer (continued). "Horizontal analysis indicated that TET2, DNMT3B, DNMT3A, and DNMT1 demonstrated much higher mutation frequency among 33 cancers." (PMID 34325709, 2021). "This study aims to investigate TET2/DNMT3A mutations and antitumor activity of a novel epigenetic agent in multiple human cancer cell lines and animal models." (PMID 34039392, 2021). "As previously reported, TET2 expression is downregulated in OC and is crucial in inhibiting cancer progression." (PMID 34429758, 2021). "CpG islands at tumor suppressor and proapoptotic gene promoters are mostly hypermethylated in cancer cells due to DNMT overexpression or gene mutations (e.g., IDH1, SDH, TET2), which lead to uncontrolled division and growth of cells." (PMID 34199020, 2021). "We also made similar observations for numerous other TSGs, particularly MLH1, TET2 and CDKN2A, with them often being hypermethylated much more frequently than mutated in numerous cancer types." (PMID 34871444, 2021). "In AML tumors, TET2 and IDH1/2 mutations are mutually exclusive, confirming that inhibition of TET2 is critical for mutant IDH1/2-driven cancer pathogenesis." (PMID 32764295, 2020). "I particularly emphasize the potential applications of targeting Tet2 to influence normal and malignant cancer-immunity crosstalk." (PMID 33184433, 2020). "We observed that TETs expression especially TET2 and TET3 was closely associated with AML among various human cancers." (PMID 32209730, 2020). "Although many Tet2 interactors have been identified in both immune and cancer cells, several principal questions are waiting for answers." (PMID 33184433, 2020). "Manipulation of the activity of Tet2 interactors via small molecules or other modulators would be useful for future cancer-immune therapy." (PMID 33184433, 2020). "Collectively, Tet2 is critical to the cancer-immunity crosstalk, which is essential for both cancer development and anticancer immune responses." (PMID 33184433, 2020). "This will require additional insights into how Tet2 works, and how it is modulated in various types of mammalian cells, including both cancer and immune cells." (PMID 33184433, 2020). "Ten-eleven translocation (TET) protein 2 (TET2), an evolutionarily conserved dioxygenases, is reported to be involved in various malignant tumor developments." (PMID 32774157, 2020). "The epigenomic regulation of gene expression by TET2 and its involvement in carcinogenesis have been studied in various cancers, but its relationship with metabolic disorders has only emerged recently." (PMID 33551821, 2020). "Based on the TCGA transcriptomic data, a number of cancer types, including HCC, we observed that lower TET2 expression levels in cancer tissues when compared with matched normal tissues." (PMID 33097695, 2020). "For instance, how do these interactors assist Tet2 dysregulation-mediated cancer transformation as well as anticancer immune responses?" (PMID 33184433, 2020). "EBF1 can interact with the methylcytosine dioxygenase enzyme TET2 in several cancer types, suggesting a role of EBF1 in regulating DNA methylation." (PMID 33061809, 2020). "Several post-translational modifications of TET2 have been reported to alter its stability and activity in cancer cell lines, including lysine acetylation." (PMID 32895473, 2020). "It has been shown that TET2 expression is often silenced post-transcriptionally in human cancers, such as by mircroRNA-mediated gene silencing." (PMID 32934200, 2020). "With regards to potential clinical usage, it is hard to precisely target Tet2 for treating cancer progression, due to its inactivation in various cancer cell types." (PMID 33184433, 2020). "Overall, these results indicate that although HDACi treatment has an anti-cancer effect, it can also significantly downregulate TET2 activity, impairing DNA demethylation capacity and potentially counteracting a therapeutic effect." (PMID 32726753, 2020).
cancer (continued). "TET2 is categorized as one of the most frequently categorized malignancies, and TET2 alteration is considered as an early onset of cancers." (PMID 31947879, 2020). "Epigenetic modifications, particularly aberrant methylation of cancer-related genes such as Tet methylcytosine dioxygenase 2 (TET2) and DNA methyltransferase 3A (DNMT3A), are common abnormalities in MDS." (PMID 32849799, 2020). "Numerous regulatory mechanisms have either directly or indirectly been demonstrated to regulate Tet2 activities or expression levels in immune-cell subsets and cancer cells." (PMID 33184433, 2020). "There is still a lot to grasp regarding the physiological and pathological roles of Tet2 in other aspects (e.g., metabolism) in both immune and cancer cells." (PMID 33184433, 2020). "Future work will focus on the accurate targeting of Tet2 in the context of different specific cell types, among both cancer and immune cells." (PMID 33184433, 2020). "Collectively, the most frequently mutated cancer myeloid genes were ASXL1 (47%), TET2 (37%), RUNX1 (27%) and SRSF2 (17%)." (PMID 30787430, 2019). "How can researchers optimize the potential practical value of TET2 alteration or modification for improving early detection of cancer and for immunotherapies?" (PMID 31033072, 2019). "Additional studies are required to shed light on the potential therapeutic role of disrupting TET2 pathway to augment genome instability for the treatment of cancer." (PMID 31001476, 2019). "Cell lines expressing high levels of TET2 mRNA were observed for most tissues, perhaps reflecting involvement in conserved biological or cancer-relevant processes." (PMID 31231651, 2019). "Based on our work and those published by others, we presumed that endogenous R-2HG in IDH-mutant cancers most likely contributes to cancer initiation via inhibition of TET2 and probably also other epigenetic pathways." (PMID 29686311, 2018). "These included several candidate tumor suppressor genes, such as ABLIM1, CYFIP2, VPS13A, SERPINI1, TET2, HTRA4, UBE2L6, as well as oncogenes/genes implicated as biomarkers in other cancers, such as FAM65B and TCF7L2." (PMID 27385100, 2016). "TET catalyzes the oxidation of 5-mC into 5-hmC, and downregulation of TET, especially TET2, have been reported in human cancers." (PMID 27050164, 2016). "In vitro studies of TET2 in cancer cells confirm that these promoters are resistant to methylation gain independently of sustained TET2 expression." (PMID 25853800, 2015). "This approach identified candidate variants in known cancer genes, including in BCOR, NOTCH2, TET2, NF1, EZH2, and JAK1." (PMID 28721364, 2015). "This is a requirement for understanding their roles in cellular transformation, because mutations detected in cancer can inactivate or impair DNA methylation (for example, DNMT3A mutations) or DNA demethylation (for example, TET2 or IDH mutations)." (PMID 25632305, 2015). "In summary, TET1, TET2, and TET3 are required for maintenance of 5hmC at genes susceptible to hypermethylation in cancer." (PMID 24958354, 2014). "TET2 was first suspected to have a role in cancer when six patients with either secondary AML (sAML) or MDS were noted to have minimal deletions via FISH on chromosome 4q24." (PMID 24622842, 2014). "Of the TET2 mutations (only accounting for frameshift, nonsense, and missense mutations) reported in COSMIC across all human cancers, 71% (2074/2923) occur in hematological malignancies, with the remaining 29% (849/2923) reported across a plethora of solid tumors." (PMID 40116537, 2025). "Further in vitro and in vivo studies revealed that TET2 could be silenced by miR22, resulting in hypermethylation of the miR200c promoter and enhanced cancer stemness." (PMID 40014756, 2025).
cancer (continued). "The use of metformin stabilized TET2 and restored 5hmC levels after rescuing Ser99 phosphorylation, offering a new perspective on using drug repositioning in epigenetic reprogramming for cancer treatment." (PMID 40427015, 2025). "As research progresses, the development of TET2-targeted therapies could significantly impact cancer treatment paradigms." (PMID 41169875, 2025). "Similarly, to the best of our knowledge, research has yet to identify an agonist of TET2, which is expressed at low levels or inactivated in various cancers." (PMID 41354740, 2025). "However, in vitro studies showed that TET2-activated miR200c downregulates PKCζ, contributing to a decrease of cancer stem cell pool." (PMID 40014756, 2025). "Of the high‐frequency recurrent TET2 mutations reported in human cancers, the majority are nonsense variants, with residues 544, 550, and 1516 being particularly affected." (PMID 40116537, 2025). "Genetic alterations in TET2 are frequent in numerous cancer settings, although data regarding the biological consequences of TET2 loss in nonhematological malignancies is limited." (PMID 40116537, 2025). "TET2-mutant cancers may respond differently to hypomethylating agents (like azacitidine or decitabine)." (PMID 41440942, 2025). "The interplay between TET2, cell proliferation, and apoptosis highlights its potential as a therapeutic target in cancer treatment, where modulation of TET2 activity could enhance the efficacy of existing therapies and improve patient outcomes." (PMID 41169875, 2025). "Mechanisms to explain loss of TET2 activity in cancer are not well established, but include reduction of α-KG levels in some cancers as well as loss of TET2 expression." (PMID 39388288, 2024). "Unlike TET1 and TET3, TET2 is frequently mutated and characterized by loss of function in myeloid cancers, implying the critical role of TET2 across cancers." (PMID 39564571, 2024). "The effect of DNA methyltransferase (DNMT) 1 gene status on TET2 expression following DNMT inhibitor treatment remains unknown in cancer." (PMID 39057134, 2024). "DM patients who have TET2 mutations may have abnormal regulation of the AMPK-TET2-5hmC pathway and would be more susceptible to cancer, including MDS." (PMID 38305890, 2024). "The TET2 expression in cancer tissues was significantly reduced, and its recovery could effectively inhibit the malignant biological behavior of OSCC." (PMID 38246976, 2024). "Besides TET2-dependent epigenetic reprogramming, vitamin C can also target other two vulnerabilities of cancers, that is, redox balance and oxygen sensing." (PMID 39564571, 2024). "The deletion of DNMT1 may have released its repression on the TET2 promoter in the cancer cells and prime these cells for TET2 upregulation upon exposure to DNMTi." (PMID 39057134, 2024). "This was the first study to show that DNMT3A and TET2 methylation levels change with the degree of cancer differentiation and that DNMT3A knockdown or TET2 overexpression could effectively inhibit the proliferation and migration of OSCC." (PMID 38246976, 2024). "Moreover, a previous study revealed that the expression of TET2 and microRNA-200 is correlated, and their dysregulation can indirectly lead cancer stem cells to a luminal-cell-like state through the inhibition of protein kinase C zeta (PRKCZ)." (PMID 39201247, 2024). "While the benefit of smoking cessation is widespread across cancer prevention, the mechanistic implications of the present study for patients with known TET2 or JAK2 V617F CHIP may be potentially meaningful." (PMID 37601662, 2023). "Here, we report the epitranscriptomic mechanism of how TET2 could be regulated in cancer, providing a rationale for developing therapeutic strategies for TET2 intervention." (PMID 37643007, 2023).
cancer (continued). "Our data argue in favor of using hypomethylating agents for chemoresistant disease or as first-line therapy in patients with biallelic TET2-mutated AML and demonstrate the importance of considering mutant allele dosage in the implementation of precision medicine for patients with cancer." (PMID 36480300, 2023). "Notably, DNMT1, NSUN2, and TET2 showed consistent positive correlations with WDHD1 expression across all types of cancers." (PMID 37759234, 2023). "The repression of TET2 might reflect more diverse transcriptional regulation, which is required for tumorigenic properties of cancer cells." (PMID 37643007, 2023). "Whether itaconate inhibiting TET2 catalytic activity leads to cancer requires further investigation." (PMID 38042791, 2023). "Notably, Tet2-KO HSCs relative to WT enriched for transcriptional signatures of cancer, myelopoiesis, and dysregulation of lymphopoiesis and hemopoiesis upon IL1β stimulation but not in steady state." (PMID 38062031, 2023). "Our results indicate that non-catalytic TET2 similar to catalytic mutant TET2 is important in regulating essential mechanisms pertaining to fly survival, locomotion and circadian rhythms that warrants further assessments to better understand the role of TET2 in development and cancer." (PMID 36989121, 2023). "Furthermore, the association between the DNA methylation level and gene expression of TET2 in selected cancers in TCGA database was analyzed using MEXPRESS." (PMID 35223782, 2022). "Whereas TET2 global deacetylation mediated by histone deacetylases, 1 and 2 (HDAC1 and 2) leads to reduced enzymatic activity triggering the emergence of abnormal DNA methylation profiles typically associated with cancer." (PMID 35159097, 2022). "Collectively, it is implied that TET2 and TET3 could be involved in the differential regulation seen in cancers, however its exact association still needs to be explored further." (PMID 35372016, 2022). "TET2 expression was significantly down-regulated in cancer samples (P = 3.250346E-05)." (PMID 35480097, 2022). "Thus, up-regulated TET2 and TDG was significant to the dedifferentiation process, which is consistent with TET2-mediated DNA demethylation in somatic cellular reprograming, stem cell maintenance, and cancer cell quiescence." (PMID 36110329, 2022). "The tissues also contain non-TET2 expressing non-cancer cells (e.g., lymphocytes, stromal cells)." (PMID 34905094, 2022). "Finally, early B-cell factor 1 (EBF1) has been identified as a TET2 interaction partner in IDH-mutant cancers." (PMID 36213002, 2022). "Finally, we reported physical interactions between FOXA1 with TET1 and TET2 both in an in vitro setup and in vivo at physiological levels in MCF-7 cells, adding further support for FOXA1 attracting TET1 and TET2 to induce local demethylation in cancer cells." (PMID 35440061, 2022). "Future studies that investigate the effectiveness of TET2 inhibitors, combined with chemotherapeutics against proliferative cancer cells, may be relevant for iCCA research." (PMID 34905094, 2022). "A highly relevant study showed increases in the expression of TET2 and 5hmC in a number of cancers that modulated the expression of TNF-α signalling components and facilitated chemotherapy resistance in slow-cycling cancer cells by restraining proapoptotic signalling." (PMID 34905094, 2022). "The epigenetic enzyme TET2 may be a key factor controlling the numbers and survival of slow-cycling cancer cells as well as tumour recurrence." (PMID 34135460, 2021). "IDH1/2 and TET2 mutations are not mutually exclusive but rather coexist in a large fraction of patients in some cancers such as AITL." (PMID 33805247, 2021). "These opposite results indicate that TET2-mediated regulation of PD-L1 gene expression may be largely dependent on the cancer/tissue types." (PMID 34064441, 2021).